NFATC1 (nuclear factor of activated T cells 1)
Description:
Plays a role in the inducible expression of cytokine genes in T-cells, especially in the induction of the IL-2 or IL-4 gene transcription. Also controls gene expression in embryonic cardiac cells. Could regulate not only the activation and proliferation but also the differentiation and programmed death of T-lymphocytes as well as lymphoid and non-lymphoid cells. Required for osteoclastogenesis and regulates many genes important for osteoclast differentiation and function (By similarity).
Synonyms: NF-ATc; NFATc; NFAT2; NF-ATc1.2
Tractability: Small molecule: a high-quality ligand is known; it has a high-quality binding pocket. PROTAC: ubiquitination databases record sites on it; its protein half-life has been measured; a small molecule that binds it is known.
Target class: Other cytosolic protein
Gene: Protein-coding gene on chromosome 18 (79,395,856 to 79,529,325, forward strand). Ensembl gene ENSG00000131196.
Subcellular location: Cytoplasm; Nucleus
Subcellular location (Human Protein Atlas): Nuclear bodies; Nucleoplasm
Pathways (Reactome):
Immune System: CLEC7A (Dectin-1) induces NFAT activation; Calcineurin activates NFAT; FCERI mediated Ca+2 mobilization
Developmental Biology: Differentiation of naive CD4+ T cells to T helper 1 cells (Th1 cells)
Signal Transduction: Ca2+ pathway
Gene Ontology:
Molecular function: protein binding; protein phosphatase 2B binding; sequence-specific double-stranded DNA binding; DNA-binding transcription activator activity, RNA polymerase II-specific; DNA-binding transcription factor activity; DNA-binding transcription factor activity, RNA polymerase II-specific; FK506 binding; mitogen-activated protein kinase p38 binding; RNA polymerase II cis-regulatory region sequence-specific DNA binding; RNA polymerase II-specific DNA-binding transcription factor binding; DNA binding
Biological process: calcineurin-NFAT signaling cascade; intracellular signal transduction; negative regulation of inflammatory response; negative regulation of vascular associated smooth muscle cell differentiation; positive regulation of DNA-templated transcription; positive regulation of transcription by RNA polymerase II; aortic valve morphogenesis; negative regulation of Wnt signaling pathway; pulmonary valve morphogenesis; regulation of DNA-templated transcription
Cellular component: chromatin; cytoplasm; nuclear body; nucleoplasm; nucleus; cytosol; transcription regulator complex
Genetic constraint (gnomAD): Loss-of-function variants: 23 observed, 70.65 expected, observed/expected ratio (o/e) 0.33, 90% interval 0.23 to 0.46. The upper end of that interval is the gene's LOEUF score, 0.46, which puts it in group 2 of 6, group 1 being the genes least tolerant of losing a copy. Missense variants: 1,356 observed, 1,306.8 expected, observed/expected ratio (o/e) 1.04, 90% interval 0.99 to 1.09. Synonymous variants: 704 observed, 605.61 expected, observed/expected ratio (o/e) 1.16, 90% interval 1.09 to 1.24.
Gene-disease validity (ClinGen):
ClinGen rates the evidence that NFATC1 causes each of these diseases.
congenital heart disease (autosomal dominant): Disputed. A heart disease that is present at birth.
Homologues: Orthologues: macaque NFATC1 (97% identical), mouse Nfatc1 (84% identical), guinea pig NFATC1 (81% identical), pig NFATC1 (80% identical), rat Nfatc1 (80% identical), dog NFATC1 (80% identical), chimpanzee NFATC1 (74% identical), tropical clawed frog nfatc1 (72% identical), zebrafish nfatc1 (54% identical). Paralogues in human: NFATC3 (40% identical), NFATC2 (39% identical), NFATC4 (33% identical), NFAT5 (25% identical).
Diseases named in the same sentence as NFATC1 in open-access papers:
NFATC1 is named in the same sentence as 214 diseases in open-access papers, as found by Europe PMC text mining. Sharing a sentence is not in itself a finding about the gene and the disease. The quoted sentences say what the papers report.
osteoporosis (91 papers, 2009 to 2026). A condition of reduced bone mass, with decreased cortical thickness and a decrease in the number and size of the trabeculae of cancellous bone (but normal chemical composition), resulting in increased fracture incidence. "NFATc1 activation is necessary and beneficial for OC formation and induces the expression of many genes involved in OC differentiation and function, and NFATc1 is closely associated with inflammation-related osteoporosis." (PMID 36644540, 2023). "TH decreased the expression of the NFATc1/c-Fos pathway, leading to decreased osteoclast differentiation, and TH also improved bone loss in the postmenopausal osteoporosis rat model." (PMID 36297038, 2022). "Inhibition of osteoclast differentiation associated with NFATc1 has previously been reported as a treatment strategy for osteoporosis." (PMID 36193131, 2022). "Our research reveals a novel Bhlhe40/c-Fos/Nfatc1 axis involved in regulating osteoclastogenesis and shows that osteoporosis caused by estrogen deficiency and aging can be rescued by regulating Bhlhe40 in mice." (PMID 35619122, 2022). "Therefore, CS inhibits Nfatc1 transcription due to K310 deacetylation, preserving bone density from osteoporosis caused by OVX or inflammatory bone resorption triggered by lipopolysaccharide (LPS)." (PMID 40153585, 2025). "ICT significantly inhibited OC differentiation and the expression of related genes (Trap, Mmp9, and Nfatc1), reduced bone loss, and improved osteoporosis and bone trabecular structure, and inhibited the levels of TRAP and RANKL in the serum and increase the level of osteoprotegerin (OPG)." (PMID 41019997, 2025). "In the present research, we focused on the potential therapeutic effects of LrB on RANKL-induced osteoclast activity in vitro and an ovariectomy (OVX)-induced osteoporosis mouse model in vivo, and evaluated the effect of LrB on ROS, NFATc1 and MAPK pathways to elucidate the underlying mechanisms." (PMID 31367247, 2019). "Therefore, zinc might be a good therapeutic candidate for preventing osteoporosis and arthritis caused by NFATc1 activation in osteoclasts." (PMID 24088289, 2013). "In normal mice, cyclosporin A treatment induces osteoporosis by inhibiting NFATc1-mediated osteoblast formation, suggesting that NFATc1 plays a more critical role in osteoblasts than in osteoclasts during physiological bone remodeling." (PMID 41559024, 2026). "In conclusion, our findings indicated that Ski suppressed osteoclast formation by suppressing ERp57‐driven calcium oscillations/calcineurin/Nfatc1 signalling, thus establishing Ski as a promising therapeutic alternative for osteoporosis." (PMID 40797290, 2025). "While basal autophagy activates NFATc1 and c-Fos to promote osteoporosis pathogenesis, UA suppresses c-Fos/NFATc1 induction, inhibits osteoclastogenesis, and attenuates pathological autophagy." (PMID 40421013, 2025). "The NFATc1 mRNA increased in the alveolar bone of postmenopausal women with osteoporosis (P11–P20) according to RT‐qPCR analysis." (PMID 40051055, 2025). "Osteoprotective: ↓ bone loss in both RANKL-induced osteoporosis and OVX mice by suppressing the activity of NF-kB, c-Fos, and NFATc1, master transcriptional factors for osteoclastogenesis." (PMID 38794640, 2024). "We further performed western blotting assays and detected a decrease in the osteoblast marker type 1 collagen and an increase in the osteoclast marker NFATc1 (Nuclear Factor Of Activated T Cells 1), a typical sign of osteoporosis." (PMID 39617773, 2024). "NFATc1+ cells were significantly diminished in the Dmab group relative to treatment-naive patients with osteoporosis, supporting our finding of a reduced number of cOCPs in the Dmab group." (PMID 39576015, 2024). "Remarkably, these rescued mice exhibited severe osteoporosis at birth, underscoring the critical involvement of NFATc1 in bone homeostasis." (PMID 38026985, 2023).
osteoporosis (continued). "Specifically, the NFATc1 gene is involved in the process by which ZOL inhibits osteoclasts in osteoporosis." (PMID 37957146, 2023). "Cnidium lactone regulated osteoporosis by regulating c-FOS/NFATc1 signaling pathways through p38 MAPK and PI3K-Akt." (PMID 36624462, 2023). "As a pivotal signaling pathway of osteoclastic differentiation and function, RANKL-mediated NFATc1 activation has emerged as a novel target for the treatment of osteoporosis." (PMID 35721216, 2022). "In vivo, kirenol (2–10 mg/kg) reduced ovariectomy (OVX)-induced osteoporosis, as demonstrated by the decrease in the osteoclast number and the downregulation of Cav-1 and NFATc1 expression." (PMID 35163999, 2022). "Chrysanthemum morifolium water extract inhibits differentiation of bone marrow-derived macrophages by regulating PLCγ2/CREB/c-fos/NFATc1 signaling pathway, thereby alleviating osteoporosis." (PMID 36276853, 2022). "The mechanisms of inhibition were via suppression of osteoporosis-related protein expression (NFATc1 and c-Fos), gene expression (Nfatc1, Ca2, Acp5, mmp9, CtsK, Oscar, and Atp6v0d2), and inhibited bone loss induced in the OVX model." (PMID 33859705, 2021). "These experimental results indicated that SR inhibits osteoclast differentiation and increases osteoblast activity in the OVX-induced osteoporosis model, and this effect is mediated by NFATc1 and BMP-2 similar to the in vitro experimental results." (PMID 35058781, 2021). "Using ovariectomized rats as a model, this work demonstrated that the AKT/GSK3β/β-catenin/NFATC1 signaling pathway is a target in osteoporosis treatment." (PMID 31196133, 2019). "Overall, our findings suggested that ECAP suppresses RANKL-induced osteoclastogenesis through NF-κB and NFATc-1 signaling pathways, and has the potential for use in osteoporosis treatment." (PMID 28468652, 2017). "This SNP is located in nuclear factor of activated T cell 1 (NFATc1), a transcription factor on chromosome 18, which has recently been shown to be related to osteoporosis, bone metastasis, and rheumatoid arthritis." (PMID 20018015, 2009). "Aberrant DNA methylation, a significant epigenetic change, influences osteoporosis by regulating the expression of genes associated with bone metabolism (e.g., RUNX2, NFATc1, SOST) and modifying immune cell activities, thereby facilitating inflammatory bone loss." (PMID 41282636, 2025). "The nuclear factor of activated T-cells (NFATC1), which is the primary switch that regulates the differentiation of osteoclast precursor cells, is transcriptionally activated under microgravity, leading to osteoporosis." (PMID 39917743, 2025). "Dex causes osteoporosis by increasing oxidative stress, decreasing antioxidant markers, reducing bone growth markers (OPG and OCN), and increasing bone turnover and resorption markers (NFATc1, RANKL, ACP, ALP, IL-6, and TNF-α)." (PMID 38247490, 2024). "In addition, TRPV4 knockdown suppressed osteoclast differentiation and osteoporosis induced by ovariectomy through calcium-calcineurin-NFATc1 pathway." (PMID 37608122, 2023). "In conclusion, our study demonstrated for the first time that the MCU inhibitor RR was able to inhibit osteoclast formation and bone resorption by inhibiting ROS, P38 MAPK, and NFATc1 and validated its potential therapeutic effects in osteoporosis animal models." (PMID 36148414, 2022). "Additionally, kirenol protects against OVX-induced osteoporosis by suppressing osteoclastogenesis and the Cav-1/NFATc1 signalling pathways both in vitro and in vivo." (PMID 35163999, 2022). "With respect to osteoclasts, the transcription factor nuclear factor of activated T cells c1 (NFATc1) is the primary driver of osteoclast maturation and activity; the down-regulation of NFATc1 expression and activation is therefore a key goal in osteoporosis prevention." (PMID 35563167, 2022).
osteoporosis (continued). "In conclusion, the OSE-mediated inhibition of the RANKL-induced osteoclast differentiation is regulated by the suppression of the expression of c-Fos/NFATc1, a master factor in osteoclast formation, thus highlighting its effective application for the treatment of osteoporosis." (PMID 36193131, 2022). "We found that WCM ameliorated estrogen deprivation-induced bone loss, a hallmark of osteoporosis and the anti-osteoporotic effects of WCM and WCM-PE could be attributed to its potential to suppress osteoclastogenesis by downregulating c-Fos/NFATc1." (PMID 34068461, 2021). "Combining previous data, we thus hypothesis whether disulfiram inhibited ethanol-induced osteoporosis via NFATc1." (PMID 31596733, 2019). "In conclusion, our results suggest that AP inhibits estrogen deficiency-induced bone loss in mice via the suppression of RANKL-induced osteoclastogensis and NF-κB and NFATc1 activities and, thus, might have therapeutic potential for osteoporosis." (PMID 26593901, 2015). "Consequently, mice lacking INPP4B suffer from bone loss and osteoporosis, as INPP4Bα acts on intracellular calcium to inhibit the nuclear localization of NFATc1 and subsequently the transcription of osteoclast-specific target genes." (PMID 40573111, 2025). "In particular, the inhibitory effects of NaPPS on CTK, MMP-9, NFATc1, c-Fos and AP-1in OC could translate to it beneficial effects in the prevention of osteoporosis and other bone-erosive diseases such as rheumatoid arthritis and bone diseases associated with excessive bone resorption." (PMID 29720166, 2018). "Liu44 further demonstrated in a mouse orthopedic study that a singleton therapeutic agent for osteoporosis can gain a coupled effect on the stimulation of bone formation by the Wnt/GSK3β/β-catenin pathway and on the suppression of bone resorption by the NF-κB/c-fos/NFATc1 pathway." (PMID 28931847, 2017). "Among the MAPKs, p38 plays a crucial role as an essential regulator of NFATc1 induction, which is required for RANKL-mediated osteoclastogenesis, making it a potential target for treating osteoporosis." (PMID 39894822, 2025). "By reducing NFATc1 expression in osteoclasts, β-hydroxybutyric acid (BHB) inhibits osteoclast differentiation and rescues the osteoporosis phenotype." (PMID 40153585, 2025). "In this study, we found that EA inhibited TRAF6, NFATc1, pAKT/AKT and pNF-κB/κB expression downstream of RANK, suppressed osteoclast differentiation, and effectively delayed oxidative stress-induced osteoporosis, consistent with previous studies." (PMID 39152382, 2024). "An EAHM herb, Acorus tatarinowii, contains α-asarone (ASA), which can prevent osteoporosis by suppressing osteoclastogenesis via AKT, p38 and NF-κB, followed by the NFATc1/c-Fos signaling pathway." (PMID 39204089, 2024). "Molecular docking of osteoclast associated protein receptors with BCA, we found that BCA likely targets NFATc1, ERK and JNK to prevent osteoporosis." (PMID 38191438, 2024). "Recent studies have found that other compounds also alleviate the osteoclastogenesis and ovariectomy-induced osteoporosis via suppressing RANKL-induced ROS production and NFATc1 activation." (PMID 36148414, 2022). "Recent studies have found that other compounds also alleviate osteoclastogenesis and ovariectomized osteoporosis by inhibiting RANKL-induced activation of ROS and NFATc1 at relatively low doses." (PMID 36388169, 2022). "This information suggests that NFATC1, cSRC, MMP-9 and Cathepsin K were the four core indicators of osteoclastogenesis involved in osteoporosis." (PMID 36431913, 2022). "In this study, we concluded that dictamnine inhibits osteoclastogenesis by inhibiting the activities of ROS, NF-κB, and NFATc1 in vitro and deters the development of OVX-induced osteoporosis mouse models." (PMID 36388169, 2022). "The current study showed that GPF attenuates osteoclastogenesis and prevents ovariectomy-induced osteoporosis via inhibiting ROS and MAPK/c-Fos/NFATc1 signaling pathway." (PMID 33897430, 2021).
osteoporosis (continued). "MVP also affords a greater selectivity than other osteoporosis therapies as it is predominantly expressed in osteoclasts and also involved in the RANKL-induced Ca2+-calcineurin-NFATc1 pathway." (PMID 34158848, 2021). "Ciclopirox significantly inhibited not only osteoclastogenesis through the downregulation of NFATc1 and its target genes but also bone resorption in vitro and prevented OVX-induced osteoporosis in vivo." (PMID 34361069, 2021). "In this study, we demonstrated for the first time that LrB inhibits osteoclastogenesis by repressing ROS, MAPK and NFATc1 activities in vitro and prevents the development of OVX-induced osteoporosis mouse model in vivo." (PMID 31367247, 2019). "In conclusion, despite the limitations of this study, it can be concluded that localized stem cell administration can accelerate and enhance osseointegration in osteoporosis conditions through various evaluated markers Osx, osteocalcin, collagen type 1, RUNX2, NFATc1, TNFα, and BIV." (PMID 41585122, 2026). "Additionally, research has shown that ALDH1A1 can regulate the expression of NFATc1, a key regulator of osteoclast differentiation, and that disulfiram can act through the ALDH1A1‒NFATc1 axis as a treatment for alcohol-related osteoporosis." (PMID 40708788, 2025). "Meanwhile, one recent in vivo study has shown that this herb exerted an anti-osteoporosis effect by suppressing the activations of TRAF6 and NFATc1, both of which played imperative roles in osteoclast differentiation during the advancement of periodontal diseases." (PMID 41010928, 2025). "It would be interesting to discover whether PLH can inhibit osteoporosis through the NF-κB, MAPK, and NFATc1 pathways." (PMID 35164085, 2022). "We demonstrated that dictamnine (DIC), a novel RANKL-targeted furoquinoline alkaloid, inhibits osteoclastogenesis by facilitating the activities of reactive oxygen species (ROS), NF-κB, and NFATc1 in vitro and prevents the development of OVX-induced osteoporosis mouse models in vivo." (PMID 36388169, 2022). "Previous reports showed that patients, following organ transplantation and being treated with inhibitors of the calcineurin/NFATc1 pathway, such as cyclosporin A and FK506, often develop osteoporosis, suggesting that immunosuppression and anti-inflammation therapies inhibit bone formation." (PMID 33628851, 2021). "DC‐STAMP is a direct target of c‐Fos and NFATc1 and a master regulator of cell–cell fusion, and DC‐STAMP‐Tg mice display decreased bone mass and increased osteoclastogenesis, leading to the development of osteoporosis." (PMID 32602250, 2020). "Lutein protected ovariectomized rats from osteoporosis by reducing lipid peroxidation, inhibiting NF-κB activation, and reducing the levels of inflammatory cytokines (TNF-α, IL-6, IL-8) and osteoclast-specific marker [nuclear factor of activated T cells 1 (NFATc1)]." (PMID 34573081, 2021). "Therefore, this study applied a low-dose combination of LiCl and LY294002 to treat osteoporosis and to test whether this method can inhibit osteoclast activity and promote osteoblast activity through inhibition of the AKT/GSK3β/β-catenin/NFATC1 pathway." (PMID 31196133, 2019). "In conclusion, our data demonstrated that OMT impaired ROS mediated SREBP2 activity and downstream NFATc1 expression during osteoclastogenesis, suppressed OVX-induced osteopenia in vivo, which suggested that OMT could be a promising compound for medical treatment against osteoporosis." (PMID 34136493, 2021). "Collectively, Asperpyrone A attenuates RANKL‐induced osteoclast formation via suppressing NFATc1, Ca2+ signalling and oxidative stress, as well as MAPK and NF‐κB signalling pathways, indicating that this compound may become a potential candidate drug for the prevention or treatment of osteoporosis." (PMID 31612613, 2019).